LDHA (lactate dehydrogenase A)
Diseases named in the same sentence as LDHA in open-access papers (continued):
Sharing a sentence is not in itself a finding about the gene and the disease.
keloid (1 paper, 2025). An irregularly shaped, elevated mark on the skin caused by deposits of excessive amounts of collagen during wound healing. "Under hypoxia, PI3K/AKT signaling enhances glycolysis in keloid fibroblasts by upregulating GLUT1 and key enzymes (HK2, PFKFB3, LDHA), increasing ECAR and promoting proliferation, migration, and survival." (PMID 41424791, 2025). "The PI3K/AKT pathway drives glycolytic reprogramming in keloids, enhancing GLUT1, LDHA, and COL1 expression to boost glucose uptake, lactate production, and collagen synthesis." (PMID 41424791, 2025).
keratitis (1 paper, 2010). A corneal disease that is characterized by inflammation of the cornea. "Namely, geNorm proposed PPIA and HRPT1 and PPIA and RPL5 pairs for chemical burn-induced CorNV in Balb/c and C57BL/6 mice, respectively, while UBC and HPRT1 and UBC and LDHA were best for Candida and Aspergillus induced keratitis in Balb/c mice, respectively." (PMID 20596249, 2010).
kidney stone (1 paper, 2025). "Given the well-established role of IGF1R in influencing STAT3 phosphorylation, this study focused on the regulation of downstream LDHA by JAK2/STAT3 signaling axis and its role in kidney stone formation." (PMID 39744436, 2025).
kidney tumors (1 paper, 2023). "LDHA is overexpressed in various neoplastic tissues, and enhanced LDHA expression is associated with worse prognosis of patients with brain, liver, lung, and kidney tumors." (PMID 37547725, 2023).
laryngeal carcinoma (1 paper, 2022). Carcinoma that arises from the laryngeal epithelium. "MIF, ENO2 and LDHA were identified to be related to lipid metabolism when laryngeal cancer cells were exposed to hypoxia, which is consistent with the RNA-seq analysis of Hep2 cells exposed to hypoxia." (PMID 36042480, 2022). "Three genes, lactate dehydrogenase A (LDHA), enolase 2 (ENO2) and macrophage migration inhibitory factor (MIF), may be involved in lipid metabolism in laryngeal cancer cells." (PMID 36042480, 2022).
laryngeal squamous cell carcinoma (1 paper, 2024). A squamous cell carcinoma that arises from the larynx. "And increased E2F1 expression via the E2F1/FTH1P3/miR-377-3p/LDHA axis promoted cell viability and glycolysis in laryngeal squamous cell carcinoma." (PMID 39546499, 2024).
low grade glioma (1 paper, 2025). A grade I or grade II glioma arising from the central nervous system. "This study aimed to analyze the prognostic and diagnostic value of Lactate dehydrogenase A (LDHA) and solute carrier family 16 member 1 (SLC16A1) in low-grade gliomas (LGG)." (PMID 40782248, 2025).
lung adenoma (1 paper, 2021). A benign, well circumscribed epithelial neoplasm that arises from the bronchus or the lung parenchyma. "In this translational study, we found that the expression of LDHA, no matter mRNA or protein levels, was up-regulated in both lung adenoma and squamous cells." (PMID 33902615, 2021).
Lyme borreliosis (1 paper, 2021). "Indeed, increased PFKFB3, HK2, and LDHA gene expression has been observed in Lyme borreliosis patients, as well as increased levels of serum lactate." (PMID 33395408, 2021).
mastitis (1 paper, 2017). Inflammation of breast tissue during lactation or postpartum due to an obstructed duct or infection. "The numerically-greater expression of SLC2A1 and LDHA in INO cows during the study could indicate that these cows were more immuno-compromised because a previous study detected marked upregulation of LDHA in PMNL after a mastitis challenge." (PMID 28469842, 2017).
mesenchymal tumors (1 paper, 2024). "Interrogating The Cancer Genome Atlas (TCGA) GBM dataset for transcriptional subtypes revealed higher LDHA expression in mesenchymal tumors compared with classical and proneural subtypes." (PMID 39545414, 2024).
mismatch repair deficiency (1 paper, 2023). "Researchers found that CRC patients with both low LDHA expression and mismatch repair deficiency exhibited better disease‐free survival compared with others." (PMID 36950803, 2023).
Myocardial fibrosis (1 paper, 2025). "Additionally, myocardial fibrosis markers were significantly reduced, accompanied by a decrease in the myocardial mRNA and protein expression of glycolytic proteins, including HIF-1α, PFKFB3, GLUT1, and LDHA." (PMID 40944191, 2025).
myocardial ischemia (1 paper, 2025). A disorder of cardiac function caused by insufficient blood flow to the muscle tissue of the heart. "Moreover, the lactate dehydrogenase encoding gene LDHA, which catalyzes the conversion between pyruvate and lactic acid, can induce myocardial pyroptosis by enhancing NLRP3 lactation, thereby promoting myocardial ischemia–reperfusion injury." (PMID 40873619, 2025).
neuropathy (1 paper, 2023). A disorder affecting the nervous system that manifests with pain, tingling, numbness, and/or muscle weakness. "In conclusion, the present studies demonstrated that neuropathy upregulates angiogenesis and neuronal LDHA expression in the spinal cord." (PMID 36827154, 2023). "The marine sponge-derived natural compound aaptamine has an analgesic effect on neuropathy rats, possibly by regulating LDHA and angiogenesis." (PMID 36827154, 2023). "The marine sponge-derived natural compound aaptamine has an analgesic effect on neuropathy in rats, possibly by regulating LDHA and angiogenesis." (PMID 36827154, 2023). "Reducing LDHA translocation into the nucleus and regulating its expression could mediate the analgesic effects of aaptamine on neuropathy." (PMID 36827154, 2023). "Furthermore, inhibition of astrocyte-derived angiogenesis and neuronal LDHA expression might be beneficial in neuropathy." (PMID 36827154, 2023).
ocular melanoma (1 paper, 2021). A melanoma that arises from the structures of the eye or ocular adnexa. "Notably, we found either LDHA-deficient (lane 2) or LDHB-deficient (lane 3) ocular melanoma cells did not present with remarkable reduction of global histone lactylation." (PMID 33726814, 2021).
oncocytic tumors (1 paper, 2013). "In thyroid tissues, the LDHA and LDHB expression levels were similar in follicular, oncocytic tumors and normal tissues." (PMID 23516535, 2013). "In thyroid tissues the ratio was higher for normal thyroid tissues than for follicular tumors or oncocytic tumors.Thus, the LDHA/LDHB ratio was similar in follicular and oncocytic tumors and their corresponding cell line models, FTC-133 and XTC.UC1." (PMID 23516535, 2013).
papillary renal cell carcinoma (1 paper, 2023). A rare subtype of renal cell carcinoma, arising from the renal tubular epithelium and showing a papillary growth pattern, which typically manifests with hematuria, flank pain, palpable abdominal mass or nonspecific symptoms, such as fatigue, weight loss or fever. "Moreover, Wang Q and his research team also detected in papillary renal cell carcinoma that the most up-regulated gene was lactate dehydrogenase A (LDHA), while FH is downregulated, both involved in ATP generation." (PMID 37176098, 2023).
papilloma (1 paper, 2024). A benign epithelial neoplasm that projects above the surrounding epithelial surface and consists of villous or arborescent outgrowths of fibrovascular stroma. "By the end of the experiment, when the control animals had to be euthanized, there were no papilloma or SCC that lacked both LDHA activity and GLS expression in any of the GLSKOLDHAKO mice." (PMID 39303037, 2024). "This suggests that those papilloma that lacked both LDHA and GLS that might have formed in GLSKOLDHAKO mice probably underwent regression." (PMID 39303037, 2024).
paroxysmal AF (1 paper, 2022). "Additionally, high lactic acid content and increased lactate dehydrogenase A (LDHA) were detected in canine LA in rapid atrial-pacing-induced paroxysmal AF." (PMID 36139490, 2022). "In a canine model, paroxysmal AF increased the lactic acid content and the expressions and activities of PDK-1, PDK-4, and LDHA and the decreased the expressions of PDH and citrate synthase and the AMP/ATP ratio in canine LA." (PMID 36139490, 2022).
Renal cyst (1 paper, 2024). A fluid filled sac in the kidney. "The upregulation of LDHA (1.4×) and downregulation of LDHB (−1.8×) in renal cysts suggest increased pyruvate to lactate flux." (PMID 39000280, 2024).
retinal degeneration (1 paper, 2023). Degeneration of the retina. "Notably, alterations in LDHA isoenzymes in the retinas of sheep are linked to progressive retinal degeneration, commonly known as Bright Blindness." (PMID 38983010, 2023). "Deleting LDHA specifically in the retina leads to age-related visual function deterioration, followed by retinal degeneration." (PMID 38983010, 2023).
steatosis (1 paper, 2024). Increased lipid within the cytoplasm of cells. "As MDMG-935P potently lowered hepatic oxalate, steatosis, inflammation and fibrosis in mice with established MASH, further evaluation of GO and LDHA inhibition for concurrent treatment of MASH and associated cardiovascular disease is warranted." (PMID 39333384, 2024).
Stroke (1 paper, 2022). Sudden impairment of blood flow to a part of the brain due to occlusion or rupture of an artery to the brain. "Consistent with these previous studies, we also found that HIF-1α and LDHA, triggered by inflammatory and hypoxic responses, strikingly increased in perioperative stroke mice compared with stroke-only mice and sham mice." (PMID 35799259, 2022).
T-cell lymphoma (1 paper, 2023). "For example, LDHA-deficient autoreactive T cells can still proliferate to the same extent as wild-type autoreactive T cells in scurfy mice, suggesting that LDHA is unlikely a good target to treat T-cell lymphoma or other cancers." (PMID 37305096, 2023).
testicular tumor (1 paper, 2022). "Interestingly, Sp1 binding sites, as positive regulatory elements in the LDHA promoter, were participated in promoting LDHA transcription in testicular tumor cells." (PMID 36033372, 2022).
Thiamine deficiency (1 paper, 2017). Thiamine deficiency is a condition that occurs due to not enough thiamine (vitamin B1). "The HIF-1α target gene LDHA was induced by thiamine deficiency, and subsequently reduced following thiamine repletion, although the protein did not return to control levels." (PMID 29045486, 2017).
tongue cancer (1 paper, 2023). A malignant neoplasm affecting the tongue. "Therefore, in the next step, we performed quantitative real-time PCR analyses of PFKM, PKM2, and LDHA gene expression in tongue cancer cells to validate these hypotheses." (PMID 38132445, 2023).
Zinc deficiency (1 paper, 2025). A deficiency of the essential metal Zinc; an essential cofactor for many enzymes. "Our findings demonstrated a substantial upregulation of both LDHA and LDHB expression under zinc deficiency conditions, further supporting the accumulation of lactic acid and intracellular pH reduction in zinc-deficient rat cells." (PMID 39028478, 2025). "Furthermore, lactic acid level reduction and normalization of LDHA and LDHB expression in the ZS group suggested that zinc supplementation effectively regulates energy metabolism imbalance induced by zinc deficiency." (PMID 39028478, 2025).
tumor (1,143 papers, 2008 to 2026). "The results revealed that deficiency in LDHA lactylation also significantly suppressed tumor growth in vivo." (PMID 41190808, 2026). "The results showed that high expression of YBX1 and LDHA was associated with tumor size, T stage, and Fuhrman grade." (PMID 41507134, 2026). "To further explore the potential association between YBX1 and LDHA, we excised tumor tissues from the nude mice for histological processing, including tissue embedding and sectioning." (PMID 41507134, 2026). "In resistant cancers, increased LDHA expression has been associated with enhanced glycolysis and lactate production, supporting tumor growth and survival in hypoxic conditions." (PMID 39997327, 2025). "Extensive research indicates that LDHA expression is mostly upregulated in cancer cells, potentially linked to the metabolic reprogramming of tumor cells." (PMID 41561760, 2025). "We investigated the origin of the EV subpopulation to elucidate the mechanisms underlying Elevated peripheral LDHA-enriched extracellular vesicles (LDHA-EVs) during tumor recurrence." (PMID 40093910, 2025). "Conversely, oxidative stress induced by suppressing LDHA expression or activity weakens tumor cell resistance to AIs and increases their susceptibility to these drugs." (PMID 40303296, 2025). "Based on the characteristics of tumor metabolic transformation, inhibition of tumor energy and anabolic supply is the immediate cause for LDHA as a potential target." (PMID 41041328, 2025). "Pharmacological disruption of the lactylation axis (e.g., LDHA inhibition) or modulation of RNA-modifying enzymes (e.g., methyltransferases and demethylases) can effectively reverse tumor-associated metabolic reprogramming and epigenetic dysregulation." (PMID 40859309, 2025). "This overexpression correlates with poor prognosis, radiotherapy resistance, enhanced glycolysis and hypoxia within the tumour microenvironment, as evidenced by positive associations between LDHA expression and markers such as HIF1A and GLUT-1." (PMID 41154605, 2025). "The nutrient-deficient tumor environment, along with LDHA-mediated LA production, creates a hostile condition for tumor-infiltrating lymphocytes, leading to immune evasion." (PMID 39773913, 2025). "Intriguingly, LDHA showed a more evident correlation with immunotherapy resistance and was associated with tumor metastasis and TNM stage in NSCLC." (PMID 38981044, 2024). "It is reported that LDHA can impact tumor immune surveillance and induce the transformation of tumor-associated macrophages, highlighting its unnoticed function of LDHA in immune system." (PMID 38709280, 2024). "This study reveals the complex energy dynamics of BC, exploring the interplay between two crucial metabolic regulators, FASN and LDHA, and disease progression unveiling patterns linked to tumor aggressiveness and treatment response." (PMID 39044184, 2024). "Taken together, these findings suggest that LDHA is strongly associated with tumor immune cell infiltration." (PMID 38709280, 2024). "We found that LDHA expression is tumor heterogeneous and that its high expression is associated with poor prognosis in multiple human cancers." (PMID 38709280, 2024). "LDHA is a critical enzyme involved in lactate fermentation, which is tightly linked to the metabolic reprogramming of tumor cells." (PMID 38704368, 2024). "Recent studies have shown that LDHA drives the recruitment of immunosuppressive cells and induces the transformation of tumor-associated macrophages, highlighting its unnoticed function in the immune system." (PMID 38709280, 2024). "In summary, our findings highlight LDHA as a crucial biomarker, revealing its strong association with tumor grade and suggesting its potential role as an indicator of unfavorable prognosis in endometrial cancer." (PMID 39394200, 2024). "The results above suggested that LDHA was significantly associated with infiltrating lymphocytes in the tumor microenvironment." (PMID 39582531, 2024).
tumor (continued). "A previous report showed that LDHA-associated lactic acid production blunts tumor immunosurveillance by CD8+ T cells." (PMID 36923931, 2023). "LDHA immunoexpression in the tumour stroma was mostly noted in T3/T4 tumours (p = 0.019), and a near-significant association with a low OS was obtained (p = 0.057)." (PMID 36765947, 2023). "Tyrosine phosphorylation of LDHA increased its enzymatic activity by enhancing tetramerization and increasing cofactor association to promote the Warburg effect and tumor growth." (PMID 36732657, 2023). "The increase in LDHA level is mainly caused by the increase in tumor glycolytic activity and tumor hypoxic necrosis, which are important drivers of the immunosuppressive microenvironment." (PMID 36936929, 2023). "The reduction of LDHA levels was associated with fewer cellular transformations and delayed tumor formation." (PMID 37415191, 2023). "Compared with the WT BMDCs, the LDHA/LDHB-deficient BMDCs were less potent in suppressing tumor growth and inducing tumor-infiltrating IFN-γ–producing T cells." (PMID 36821379, 2023). "This technique also provides insight into tumor LDHA and MCT4 expression, which have been linked to tumor aggressiveness." (PMID 37233647, 2023). "The LDHA inhibitor GSK2837808A increased the susceptibility of tumor cells to autologous tumor-infiltrating lymphocytes (TIL)-mediated killing in B16 allografts." (PMID 37444583, 2023). "LDHA upregulation was associated with resistance to chemotherapy,29LDHA downregulation was associated with tumor metastases." (PMID 37326348, 2023). "After inoculation of WT mice with MC38 tumor cells, we injected cGAMP-treated WT BMDCs or LDHA/LDHB-deficient BMDCs into the tumor-bearing mice." (PMID 36821379, 2023). "For instance, LDHA-associated LA accumulation in melanoma has been shown to inhibit tumor monitoring by T and NK cells." (PMID 37853445, 2023). "We observed higher expressions of LDHA in human GBM samples, especially in astrocytes, radical glia, progenitor, microglia, tumor associated microphage and endothelial cells, supporting LDHA as a potential target for GBM therapy." (PMID 37770937, 2023). "In vivo experiments that injected a melanoma cells into mice showed that LDHA knockdown decreases PD-L1 expression, and thus makes tumor cells more susceptible to anti-PD-1 treatment." (PMID 36330529, 2022). "Notwithstanding, Boudreau and colleagues recently reported the presence of innate and acquired resistance to LDHA inhibition linked to tumor metabolic plasticity, namely through the activation of the MPK–mTOR–S6K signaling pathway leading to increased OxPhos." (PMID 35205318, 2022). "In multivariable adjusted models, up regulation of LDHA expression is associated with high tumour folate dose levels at advance NSCLC." (PMID 36615660, 2022). "Studies have also verified that an elevated LDHA level is associated with the degree of tumor differentiation, progression, and the prognosis of a cancer." (PMID 35535311, 2022). "Double LDHA/B KO decreased both proliferation and invasion and was also linked to the increase in apoptosis, thus improving mouse survival via reduction of the tumor mass." (PMID 36278433, 2022). "LDHA is associated with cancer progression and poor prognosis, since its overexpression promotes angiogenesis and tumor dissemination." (PMID 36077374, 2022). "Up-regulation of LDHA has been demonstrated in several cancers and associates with carcinogenesis and tumor progression." (PMID 33407494, 2021). "Elevated LDHA expression is associated with poor outcomes in tumor patients due to the blunt immune surveillance caused by lactic acid accumulation." (PMID 34307169, 2021). "In PDA patients, a positive association of LDHA expression with disease stage, tumor size and differentiation was observed." (PMID 33804240, 2021).